SDC4 (syndecan 4)
Description:
Cell surface proteoglycan which regulates exosome biogenesis in concert with SDCBP and PDCD6IP.
Synonyms: SYND4; amphiglycan; ryudocan
Tractability: Small molecule: an approved drug acts on it. Antibody: UniProt places it where antibodies can reach, with high confidence; its Gene Ontology location is reachable by antibodies, with high confidence; UniProt predicts a signal peptide or a membrane-spanning region; the Human Protein Atlas places it where antibodies can reach. PROTAC: ubiquitination databases record sites on it; its protein half-life has been measured.
Gene: Protein-coding gene on chromosome 20 (45,325,288 to 45,348,425, reverse strand). Ensembl gene ENSG00000124145.
Subcellular location: Membrane (Isoform 1); Secreted; Secreted (Isoform 2)
Subcellular location (Human Protein Atlas): Golgi apparatus; Plasma membrane; Predicted to be secreted
Pathways (Reactome):
Disease: Attachment and Entry; Defective B3GALT6 causes EDSP2 and SEMDJL1; Defective B3GAT3 causes JDSSDHD; Defective B4GALT7 causes EDS, progeroid type; Defective EXT1 causes exostoses 1, TRPS2 and CHDS; Defective EXT2 causes exostoses 2; Dengue Virus Attachment and Entry; Dengue Virus-Host Interactions; RSV-host interactions; Respiratory syncytial virus (RSV) attachment and entry
Hemostasis: Cell surface interactions at the vascular wall; Initiation of coagulation cascade; Regulation of clotting cascade
Metabolism: Glycosaminoglycan-protein linkage region biosynthesis; HS-GAG biosynthesis; HS-GAG degradation
Extracellular matrix organization: Syndecan interactions
Sensory Perception: Retinoid metabolism and transport
Gene Ontology:
Molecular function: identical protein binding; protein binding; thrombospondin receptor activity; fibronectin binding; protein kinase C binding
Biological process: negative regulation of T cell proliferation; positive regulation of exosomal secretion; positive regulation of extracellular exosome assembly; positive regulation of focal adhesion assembly; positive regulation of stress fiber assembly; regulation of fibroblast migration; ureteric bud development
Cellular component: extracellular exosome; extracellular region; cell surface; focal adhesion; Golgi lumen; lysosomal lumen; plasma membrane; costamere; membrane
Genetic constraint (gnomAD): Loss-of-function variants: 17 observed, 20.16 expected, observed/expected ratio (o/e) 0.84, 90% interval 0.58 to 1.26. The upper end of that interval is the gene's LOEUF score, 1.26, which puts it in group 5 of 6, group 1 being the genes least tolerant of losing a copy. Missense variants: 241 observed, 257.54 expected, observed/expected ratio (o/e) 0.94, 90% interval 0.84 to 1.04. Synonymous variants: 107 observed, 105.71 expected, observed/expected ratio (o/e) 1.01, 90% interval 0.87 to 1.19.
Homologues: Orthologues: chimpanzee SDC4 (98% identical), macaque SDC4 (94% identical), dog SDC4 (85% identical), guinea pig SDC4 (81% identical), mouse Sdc4 (80% identical), rat Sdc4 (79% identical), rabbit SDC4 (72% identical), zebrafish sdc4 (39% identical), tropical clawed frog sdc4 (33% identical), Drosophila melanogaster Sdc (24% identical), Caenorhabditis elegans sdn-1 (20% identical). Paralogues in human: SDC3 (40% identical), SDC2 (35% identical), SDC1 (29% identical).
Diseases named in the same sentence as SDC4 in open-access papers:
SDC4 is named in the same sentence as 172 diseases in open-access papers, as found by Europe PMC text mining. Sharing a sentence is not in itself a finding about the gene and the disease. The quoted sentences say what the papers report.
breast carcinoma (45 papers, 2008 to 2025). "A previous study on tumor tissue also reported the association between SDC4 expression and HR + breast cancer." (PMID 40694191, 2025). "SDC4 is overexpressed in several tumor types such as melanoma, and high expression levels are associated with poor prognosis in breast cancer." (PMID 38634469, 2024). "SDC4 (syndecan-4) impaired function causes the development of breast cancer, prostate cancer and many other cancers." (PMID 37248251, 2023). "SDC4 is closely associated with cancer occurrence and development including osteosarcoma, breast cancer, prostate cancer, and colorectal cancer." (PMID 36199068, 2022). "SDC4 is closely associated with the occurrence and development of osteosarcoma, breast cancer, prostate cancer, colorectal cancer, and many other cancers." (PMID 36199068, 2022). "SDC4-silenced breast carcinoma cells show decreased ability to form bone metastasis in mice and reduced SDC4 expression is associated with reduced metastatic potential in testicular germ cell tumors." (PMID 34282767, 2021). "ADAMTS-15 decreases the migration of MDA-MB-231 and MCF-7 breast cancer cells in association with the increased cell surface expression of SDC4." (PMID 34282767, 2021). "As well, some authors found that syndecan-4 inhibited breast carcinoma cell invasion and was associated with good prognosis." (PMID 32566253, 2020). "Many HSPGs and their associated enzymes have been associated with the disease, with both SDC1 and SDC4 showing strong involvement with breast cancer." (PMID 32398079, 2020). "One study found that syndecan-4 inhibited breast carcinoma cell invasion, and its expression in human breast carcinoma was described as being associated with good prognosis." (PMID 26869927, 2016). "In addition, high levels of SDC4 gene expression are significantly associated with estrogen receptor-positive breast carcinomas, corroborating the notion of a relationship between SDC4 and estrogen/estrogen receptor signaling." (PMID 31752080, 2019). "For example, shedding of SDC4 can influence various biological behaviors of breast cancer cells, including cell adhesion, migration, and invasion, which may be associated with the progression and metastasis of breast cancer." (PMID 40426865, 2025). "Thus, this study primarily aimed to investigate whether pre-diagnostic serum levels of SDC1 and SDC4 were associated with breast cancer risk in a prospective population-based cohort." (PMID 40694191, 2025). "Moreover, we evaluated whether the modified levels of syndecan-4 caused by IGF-IR depletion affects breast cancer cell behaviour." (PMID 28079144, 2017). "It has been reported that trastuzumab, a monoclonal recombinant antibody targeting HER2 that is commonly used to treat HER2-positive breast cancer, reduces the expression of SDC4 in anoikis-resistant endothelial cells." (PMID 40076757, 2025). "Gene silencing confirms the requirement of SDC4 in the metastasis of human breast carcinoma cells in mice." (PMID 38634469, 2024). "SDC1 participates in establishing a permissive lung microenvironment for breast cancer metastasis, while SDC4 engages with EGFR to sustain cell cycle progression in head and neck carcinoma." (PMID 38546390, 2024). "In a preclinical study, it was demonstrated that preincubating highly metastatic mouse 4T1 breast cancer cells with anti-SDC4 antibodies curtailed the early steps of metastasis in the bone of a mouse model." (PMID 36980680, 2023). "This study suggested that IGFR plays a protective role against breast cancer aggressiveness by sustaining the expression of SDC4 and integrins for binding to fibronectin and laminin in ERα-expressing MCF-7 cells." (PMID 36980680, 2023). "Taken together, these findings highlight the prognostic significance of SDC1 and SDC4 in breast cancer." (PMID 36980680, 2023).
breast carcinoma (continued). "GIPC1 silencing can result in cell cycle arrest in breast cancer cells and regulate cell adhesion and motility through interaction with syndecan-4 (SDC4) via the PI3K signaling pathway." (PMID 38041134, 2023). "Only one recent study by Dr. Götte and his group shows that SDC4 is a target of miRNA in breast cancer." (PMID 36980680, 2023). "In this regard, it has been reported that the humanized monoclonal antibody trastuzumab used for breast cancer treatment can interact with SDC4, resulting in reduced proliferation, invasion, and angiogenesis of anoikis-resistant endothelial cells." (PMID 36980680, 2023). "On the other hand, regarding the involvement of another member of the SDC family as a biomarker in breast cancer, there is a conflict about the implication of SDC4 in breast cancer progression and its relation to ER/PR status." (PMID 36980680, 2023). "Mutations in GAPVD1 and other genes, estrogen- and growth factor-dependent regulation are involved in both transcriptional and post-transcriptional dysregulation of syndecan-4 in breast cancer." (PMID 36499305, 2022). "Changes in syndecan-4 expression levels can be observed in several tumor types, and it serves as a prognostic marker, such as in breast cancer, glioma, melanoma, liver cancer, and osteosarcoma." (PMID 35128576, 2022). "Syndecan-4 is involved in membrane fixation of cathelicidin LL-37 and its promigratory effect in breast cancer cells." (PMID 33810567, 2021). "SDC4 contributes to the regulation of cell motility in various cancer cell types, such as melanoma, breast cancer, lung, or cervical cancer cells." (PMID 34282767, 2021). "Syndecan-4 is also capable of modulating the effect of other matrix constituents in tumor cell migration: In breast cancer, the protease ADAMTS-15 reduces cell migration on fibronectin and laminin matrices." (PMID 33810567, 2021). "Apart from steroidal mechanisms, inhibition of the receptor tyrosine kinase IGFR was shown to downregulate syndecan-4 levels in estrogen receptor-positive breast cancer cells via an endocytic mechanism." (PMID 33810567, 2021). "While SDC4 interaction with α6β4 integrin mediates mammary carcinoma cell migration, downregulation of SDC4 by FGF2-dependent dephosphorylation of FAK promotes the migration of melanoma cells." (PMID 32916872, 2020). "The dual role of SDC4 has previously been identified by increased cellular adhesion in a human breast cancer model and increased cellular communication and signaling through decreased motility in the neural microenvironment." (PMID 29740281, 2018). "In a preclininal mouse model, targeting SDC4 on 4T1 mouse breast cancer cells inhibited early bone metastasis formation." (PMID 30237860, 2018). "Using a syngenic mouse model of breast cancer metastasis, we determined that SDC4 controls early steps of the metastasis process through an ATX-dependent mechanism." (PMID 30237860, 2018). "We showed that syndecan-4 expression in human breast carcinoma tissues correlates with positive estrogen and progesterone receptor status therefore a good prognosis." (PMID 25623282, 2015). "As a whole the data suggest that syndecan-2 in breast carcinoma plays a major regulatory role in maintaining the invasive phenotype and appears to suppress the focal adhesion promoting role of syndecan-4." (PMID 25623282, 2015). "SDC4 is a focal adhesion component in a range of cell types, adherent to different matrix molecules, including fibronectin and mediating breast cancer cell adhesion and spreading." (PMID 25140302, 2014). "Syndecan-4 mediates breast cancer cell adhesion and spreading but also binds proangiogenic growth factors and cytokines and modulates growth factor/growth factor receptor interactions regulating angiogenic processes." (PMID 23844358, 2013). "Additionally, cell surface PGs (SDC1 and SDC4) and MMPs (MMP2, MMP7, MMP9, and MMP14) implicated in breast cancer progression were further included." (PMID 41228316, 2025).
breast carcinoma (continued). "Our results suggest that SDC4 may play a role in the initiation and early progression of breast cancer." (PMID 40694191, 2025). "SDC4 is overexpressed in several tumors, e.g., in melanoma, breast cancer, and osteosarcoma." (PMID 40076757, 2025). "Furthermore, SDC4 ectodomain shedding is also relevant for breast cancer growth since it promotes cytokinesis dependent on phosphorylation in MCF-7 cells." (PMID 36980680, 2023). "This explains the cooperation between IGFR and SDC4 in ERα-positive breast cancer cells." (PMID 36980680, 2023). "To further verify whether the SDC4-PKCα pathway regulates srGAP2 phosphorylation and tension in vivo, we investigated SDC4 binding to PKCα in the fresh human breast cancer tissues and adjacent tissues." (PMID 36593959, 2023). "Furthermore, HA nanoparticle uptake was also demonstrated in breast cancer, with an internalization mechanism based on syndecan-4." (PMID 33925076, 2021). "In addition, the expression levels of SDC4 in human breast cancer links with the FGF2R complex formation, indicating that syndecan-4 regulates this FGF2R complex formation in human breast cancer." (PMID 33669066, 2021). "Interestingly, a study demonstrated that estrogen receptor beta (ERβ) silencing in MDA-MB-231 breast cancer cells induces the expression of syndecan-4, suggesting endocrine regulation of syndecan-4 in this tumor entity." (PMID 33810567, 2021). "Moreover, silencing of SDC4 expression rescued the effect of ADAMTS-15 on cell motility in breast cancer cells." (PMID 34282767, 2021). "Besides being the second most abundant HSPG produced by most breast carcinoma cell lines, syndecan-4 is involved in membrane fixation of LL-37 and its pro-migratory effect in breast cancer cells." (PMID 33810567, 2021). "SDC4-silenced breast carcinoma cells have decreased ability to form bone metastasis in mice." (PMID 34282767, 2021). "Finally, syndecan-4 is known to be expressed in breast cancer, regulating cell adhesion and spreading and also interacting with GFRs." (PMID 33669066, 2021). "Moreover, in vivo, targeting of syndecan-4 in murine 4T1 breast cancer cells inhibited the formation of early bone metastases." (PMID 33810567, 2021). "Inhibition of mammary cancer cell migration by ADAMTS-15 requires SDC4." (PMID 34282767, 2021). "Furthermore, Syndecan-2 and Syndecan-4 seem to be important regulators of breast carcinoma progression." (PMID 30922347, 2019). "Thus, a new generation of bisphosphonate, zoledronate (zoledronic acid, Zometa), downregulates the expression levels of SDC1, SDC2, and GPC1 and upregulates the expression of SDC4 in breast cancer cells of low and high metastatic capability." (PMID 25140302, 2014). "Previously, syndecan-4 has been reported to correlate significantly with high histological grade and negative estrogen receptor status, suggesting it to be a marker of poor prognosis in breast cancer." (PMID 23844358, 2013). "In the cytokine module, SDC4 and ITGB1 were identified as more active signaling pathways in breast cancer with high RiskScore." (PMID 40337509, 2025). "Analysis of lung metastasis of breast cancer in mice indicated that compared with GFP-srGAP2 + NC group, the lung metastasis was significantly reduced in GFP-srGAP2 + SDC4 KD group." (PMID 36593959, 2023). "Mechanistically, BPzoledronic acid exhibits an anti-breast cancer effect, namely the inhibition of cell proliferation, adhesion, migration, and invasion via the suppression of the expression of SDC1 and 2, whereas SDC4 was upregulated." (PMID 36980680, 2023). "Corroborating these findings in breast cancer tissues, SDC1 and SDC4 expression levels are correlated with FGF receptor complex expression." (PMID 36980680, 2023). "SDC4 is a receptor for LL-37 increasing Ca2+ levels via TRPV2 channels and increasing the motility of breast cancer cells via PI3K/AKT signaling." (PMID 34282767, 2021).
breast carcinoma (continued). "Partnership between ATXβ and SDC4 demonstrated a remarkable impact in vitro since it is necessary for ATX-induced cancer cell proliferation, and in vivo since it controls breast cancer cell metastasis." (PMID 30237860, 2018). "Taken together, these results indicated that IGF-IR regulates mainly syndecan-4, and to a lesser extent syndecan-1, expression and localization in ERα-positive MCF-7 breast cancer cells." (PMID 28079144, 2017). "In ERα-positive breast cancer cells, expression levels of syndecan-2 are controlled through the EGFR signaling pathway, in contrast to syndecan-4 where the expression is regulated by IGF-IR signaling." (PMID 28079144, 2017). "In the context of breast cancer, to date, dysregulations of SDC1 and SDC4 are better understood." (PMID 36980680, 2023). "IGFR regulates the expression of SDC4 both in the presence and in the absence of E2 in breast cancer cells.IGFR inhibitors reduced the migration of MCF-7 cells but did not have a significant effect on MDA-MB-231 cells." (PMID 34282767, 2021). "A significant role of SDC4 on IGF-I receptor activation, together with the involvement of integrins and estrogen receptors, leading to MAPK, PI3K/AKT, and/or PKC signaling pathways, in the breast cancer cell aggressiveness has been established." (PMID 32916872, 2020). "To evaluate whether SDC4 could control the ATX-dependent metastasis dissemination of cancer cells, we used the 4T1 breast cancer cells as they are communally used for their high metastatic potential to lungs and bone in syngenic BALB/C mice." (PMID 30237860, 2018). "This fascinating topic has so far not been the subject of detailed investigations, although syndecan-4 has been observed in nuclear or perinuclear areas in breast carcinoma." (PMID 26068620, 2015). "In our previous study, we demonstrated that estradiol does not affect the levels of syndecan-4 in breast cancer cells through ERα signaling although the levels of syndecan-2 are regulated by hormonal treatment." (PMID 23844358, 2013). "Both syndecan-1 and syndecan-4 are overexpressed in an estrogen receptor -negative, highly proliferative breast carcinoma subtype." (PMID 20398359, 2010). "This study aimed to examine the expression patterns of SDC1, SDC2, and SDC4 in EVs isolated from peripheral blood of neoadjuvant chemotherapy-naïve obese breast cancer patients with negative LNM (nLNM) and positive LNM (pLNM) to discover their potential as new biomarkers for LNM." (PMID 40940401, 2025). "It was found that SDC4 overexpression is a poor prognostic factor in patients with ER-negative and ER-/PR-negative breast cancer, whereas it is a good prognostic factor for all breast cancer patients analyzed, irrespective of the molecular subtypes." (PMID 36980680, 2023). "Syndecan-4 is expressed in normal human mammary epithelium, and was initially described as being overexpressed in an estrogen receptor-negative, highly proliferative breast carcinoma subtype." (PMID 33810567, 2021). "Syndecan-4 and integrins are key molecules in cell adhesion and migration on MCF-7 breast cancer cells and syndecan-4 reduced levels after inhibition of IGF-IR pathway could affect breast cancer cell behaviour." (PMID 28079144, 2017). "Our results showed that MV-enriched EVs isolated from obese breast cancer patients with pLNM contained higher SDC2, but not SDC1 and SDC4, compared to those with nLNM." (PMID 40940401, 2025). "However, thus far, the only documented substrates for ADAMTS-15 are VCAN and aggrecan, while in breast cancer, where the effects of ADAMTS-15 on cell migration were shown to involve syndecan-4, this was independent of its metalloproteinase activity." (PMID 32354091, 2020). "Thus, in estrogen receptor-negative and highly proliferative breast carcinoma subtypes, SDC1 and SDC4 were found to be overexpressed." (PMID 25140302, 2014).
breast carcinoma (continued). "Indeed, syndecan-1 and syndecan-4, two cell surface HSPG that have recently been characterized as markers of aggressiveness in breast carcinoma, are overexpressed in estrogen-negative and highly proliferative carcinomas of the mammary gland." (PMID 24083491, 2013).